KRTAP9-2 (keratin associated protein 9-2)
Description:
In the hair cortex, hair keratin intermediate filaments are embedded in an interfilamentous matrix, consisting of hair keratin-associated proteins (KRTAP), which are essential for the formation of a rigid and resistant hair shaft through their extensive disulfide bond cross-linking with abundant cysteine residues of hair keratins. The matrix proteins include the high-sulfur and high-glycine-tyrosine keratins.
Synonyms: KAP9.2; KRTAP9.2
Tractability: No criterion of Open Targets' tractability assessment is met for any kind of drug.
Gene: Protein-coding gene on chromosome 17 (41,226,648 to 41,227,652, forward strand). Ensembl gene ENSG00000239886.
Pathways (Reactome):
Developmental Biology: Keratinization
Gene Ontology:
Molecular function: identical protein binding; protein binding
Cellular component: cytosol; keratin filament
Genetic constraint (gnomAD): Loss-of-function variants: 12 observed, 13.93 expected, observed/expected ratio (o/e) 0.86, 90% interval 0.55 to 1.39. The upper end of that interval is the gene's LOEUF score, 1.39, which puts it in group 5 of 6, group 1 being the genes least tolerant of losing a copy. Missense variants: 185 observed, 203.92 expected, observed/expected ratio (o/e) 0.91, 90% interval 0.8 to 1.02. Synonymous variants: 72 observed, 68.57 expected, observed/expected ratio (o/e) 1.05, 90% interval 0.87 to 1.28.
Homologues: Orthologues: chimpanzee KRTAP9-2 (94% identical). Paralogues in human: KRTAP9-9 (94% identical), KRTAP9-7 (90% identical), KRTAP9-3 (87% identical), KRTAP9-8 (87% identical), KRTAP9-4 (85% identical), KRTAP9-6 (84% identical), KRTAP9-1 (81% identical), KRTAP4-12 (52% identical), KRTAP4-6 (50% identical), KRTAP4-9 (49% identical), KRTAP4-11 (47% identical), KRTAP4-4 (45% identical), and 35 more.